CPT1A (carnitine palmitoyltransferase 1A)
Diseases named in the same sentence as CPT1A in open-access papers (continued):
Sharing a sentence is not in itself a finding about the gene and the disease.
breast cancer (continued). "Additionally, CPT1A was also effective in differentiating patients with breast cancer from patients with benign breast disease (AUC, 0.781; 95% CI, 0.717–0.846), and in differentiating TNBC patients from healthy controls (AUC, 0.945; 95% CI, 0.891–0.998), in the test set." (PMID 33858374, 2021). "Nevertheless, CPT1A could be used as an adjunct biomarker for breast cancer diagnosis." (PMID 33858374, 2021). "Blocking FAO by CRISPR-mediated CPT1A/CPT2 KO inhibited aggressive phenotype of the radioresistant BC with down-regulation of the ERK pathway, indicating a potential metabolic target in breast cancer radiotherapy." (PMID 31803610, 2019). "Thus, targeting CPT1A/CPT2 as well as other mitochondrial FAO elements may serve as a metabolic target to enhance the efficacy of breast cancer radiotherapy." (PMID 31803610, 2019). "By comparison, CPT1A expression was only upregulated in ~2% (2/107) basal-like breast cancer samples in the TCGA dataset, and showed lower overall expression in the 105 unaltered cases compared to ER+ samples (9.99 ± 0.80), similar to the expression levels seen in breast cancer cell lines." (PMID 28101337, 2017). "CBP/P300 acetylates histone H3K27 to increase the transcription of CPT1A, thereby increasing FAO and mitigating the cytotoxic effects of tamoxifen in estrogen receptor (ER) + breast cancer cells." (PMID 40919131, 2025). "We found that RACGAP1 silencing markedly reduced the expression of CPT1A in breast cancer cell lines, while RACGAP1 overexpression enhanced the CPT1A expression." (PMID 41444950, 2025). "Analysis of the METABRIC database revealed that genes related to fatty acid metabolism, such as ACLY, CPT1A, FASN and SCD, are most highly expressed in HER2-positive breast cancer." (PMID 40303293, 2025). "IGF2BP1 directly recognizes and binds to the m6A site on CPT1A mRNA, increasing its stability and mediating IGF2BP1-induced breast cancer metastasis; this mechanism has been verified in clinical samples." (PMID 41219902, 2025). "Among the miRNAs targeting CPT1A, only one study has shown that miR-328-3p targets CPT1A to modulate FAO and repress breast cancer stemness and metastasis." (PMID 40016582, 2025). "As CPT1A and CPT1B are the rate‐limiting enzymes of fatty acid oxidation and play a critical role in maintaining the stemness characteristics of breast cancer, we first checked their levels." (PMID 38627980, 2024). "In conclusion, our study provides valuable insights into the significance of targeting FAO, particularly Cpt1a, in HER2-positive breast cancer." (PMID 39097623, 2024). "Here, we investigate the role of Carnitine palmitoyl transferase 1a (Cpt1a), a key enzyme in long-chain fatty acid (LCFA) oxidation, in ErbB2-driven breast cancers." (PMID 39097623, 2024). "L-carnitine, short-chain acylcarnitines, and three carnitine-mediated enzymes: carnitine palmitoyltransferase 1 A (CPT1A), carnitine palmitoyltransferase 2 (CPT2), and carnitine acetyltransferase (CRAT) were all up-regulated in breast cancer tissues." (PMID 37120513, 2023). "In contrast, the FASN inhibitor cerulenin reduced CPT1A expression only in NFYA wild-type cells, suggesting that NFYA regulates breast cancer malignant behavior by controlling de novo lipogenesis by regulating ACACA and FASN expression." (PMID 37268670, 2023). "We therefore collected several metastatic lesions of different organs from two patients with breast cancer within the UPTIDER rapid autopsy program and determined CPT1a and KAT2a protein expression." (PMID 36732635, 2023). "High CPT1A expression, increased FAO, and a poor prognosis are characteristics of radiation-resistant breast cancer cells." (PMID 37033619, 2023). "Drug candidates such as Etomoxir or its analogs, which inhibits CPT1A and FAO, can be developed as RT and CT sensitizers in breast cancer." (PMID 37033619, 2023).
breast cancer (continued). "Since CPT1A, CPT1B, and CPT1C belong to the CPT family, we also compared the clinical relevance of CPT1A, CPT1B, and CPT1C in total breast cancer patients and patients with various subtypes of breast cancer." (PMID 35936710, 2022). "The network analysis revealed that CPT-1A clusters with genes involved in a wide range of cancer hallmarks, with a general pattern for CPT-1A to recruit more pathways as breast cancer progresses." (PMID 36180554, 2022). "We previously reported that CPT1A, the rate-limiting regulator of the FAO process, is deregulated in canine mammary tumor tissues and cells." (PMID 34679988, 2021). "CPT1A is upregulated in MYC-overexpressing triple-negative breast cancer (TNBC), radiation-resistant breast cancer cells and radiation-derived breast cancer stem cells." (PMID 33858374, 2021). "It was also reported that CPT1A and CPT2—known target genes of PPARα—are involved in the radiation resistance of breast cancer stem cells and overall survival of breast cancer." (PMID 33466690, 2021). "To determine the diagnostic efficacy of CPT1A, we performed ROC curve analysis and compared the AUC, sensitivity, and specificity of CPT1A and three conventional clinically used biomarkers, CA15–3, CEA, and CA125, in breast cancer samples and healthy subjects." (PMID 33858374, 2021). "At the purpose to better define the function of CPT1A in the epigenetic regulation of cancer survival, in the present report we use MCF-7 cell line as in vitro model of human breast cancer." (PMID 26799588, 2016). "Analysis of TCGA and CCLE databank revealed a higher CPT1A mRNA expression in the Luminal B and/or HER2+ breast cancers." (PMID 27563814, 2016). "A 24 hr incubation with 100 ng/ml of recombinant human PRL significantly increased CPT1A mRNA levels by 1.8- and 1.6-fold in MCF-7 and MDA-MB-231 breast cancer cells, respectively (p < 0.0001 and p < 0.001, respectively) compared to untreated controls." (PMID 21294903, 2011). "We examined the expression of CPT1A, which is more widely expressed, and determined that basal mRNA levels were markedly higher in both MCF-7 and MDA-MB-231 breast cancer cells compared to the immortalized normal breast epithelial cell line 184B5." (PMID 21294903, 2011). "Notably, miR-328-3p has been identified as a regulator of CPT1A, inhibiting FAO and reducing the invasion and metastasis of breast cancer cells." (PMID 40016582, 2025). "Breast cancer (BC) and colorectal cancer (CRC) both exhibit high expression of CPT1A." (PMID 40868150, 2025). "In addition, IGF2BP1 can directly identify, bind and stabilise the m6A region on CPT1A mRNA, which in turn mediates IGF2BP1‐induced breast cancer metastasis." (PMID 39679845, 2024). "We further analyzed gene expression data from patients with breast cancer (The Cancer Genome Atlas program (TCGA) 24 and METABRIC 25) and found that high CPT1a expression (above median) in primary breast tumors of patients was significantly associated with a decreased overall survival." (PMID 36732635, 2023). "Without extra palmitate, CPT1a silencing did not decrease acetyl-CoA abundance in 3D cultured 4T1 breast cancer cells." (PMID 36732635, 2023). "Since FAO is required for the in vivo growth of breast cancer cells, it is also possible that A2780CIS cells might require CPT1A expression for cell survival in vivo." (PMID 37628819, 2023). "Similarly, also intravenous injections of CPT1a silenced 4T1, EMT6.5 and EO771-MC3B breast cancer cells reduced metastasis formation compared to control showing that this effect was not dependent on the dissemination of cancer cells from the primary tumor." (PMID 36732635, 2023). "Furthermore, by MeRIP-seq and experimental verification, we found that IGF2BP1 directly recognized and bound to the m6A sites on CPT1A mRNA and enhanced its stability, which ultimately mediated IGF2BP1-induced breast cancer metastasis." (PMID 36632454, 2023).
breast cancer (continued). "We found that FDXR correlated with mitochondrial OXPHOS genes in the ER+ breast cancer patients, while CPT1A did not have this correlation." (PMID 37207154, 2023). "Besides, it takes much longer time for obtaining the endocrine-resistant tumor tissues from breast cancer patients, future study will be needed to validate the roles of FDXR and CPT1A in endocrine resistance in vivo by patient-derived xenograft (PDX) models." (PMID 37207154, 2023). "As ACSL4 knockdown decreased CPT1A expression, we reasoned that ACSL4 might stimulate FAO in highly invasive breast cancer." (PMID 38078907, 2023). "Indeed, differences in expression of lipid metabolism related proteins in breast cancer subtypes has been demonstrated, with HER-2 positive tumours showing high expression, of PLIN1, CPT-1A, FASN, FABP4 and ACOX-1." (PMID 36180554, 2022). "A number of signalling pathways clustered with CPT-1A in HER2-positive breast carcinoma, although CPT-1A was not identified as a predictive or prognostic biomarker in this group." (PMID 36180554, 2022). "As CPT1A is a key regulator in lipid metabolism, we analyzed the correlation between serum levels of CPT1A and lipids (TG, TC, HDL-C, LDL-C, and NEFA) in the diagnosis of breast cancer." (PMID 33858374, 2021). "CPT1A mRNA levels are lower in slowly-proliferating HER2-positive and luminal B breast cancer subtypes than in highly proliferating and metastatic TNBC, suggesting that in breast cancer FAO is active more in indolent and slow progressing subtypes." (PMID 33291643, 2020). "Importantly, overexpression of CPT1A significantly decreased the proliferation and wound healing migration rates of MDA-MB231 breast cancer cells, compared to basal expression control." (PMID 30092766, 2018). "Expression of CPT1A is expressed higher in ER-positive, compared to ER-negative breast tumours and cell lines – Based on our computational findings, we sought to understand how modulating FAO affects breast cancer cell biology." (PMID 30092766, 2018). "PRL stimulation increased the expression of CPT1A (liver isoform) at the mRNA and protein levels in both breast cancer cell lines, but not in 184B5 cells." (PMID 21294903, 2011). "Treatment with PRL further increased the expression of CPT1A at both the mRNA and protein levels in breast cancer cells, with no changes observed in normal breast epithelial cells." (PMID 21294903, 2011). "The association of CPT-1A with these signalling pathways may be a consistent feature of HER2-positive breast cancer indicating the overall CPT-1A effect in cancer metabolism, conferring no additional predictive or prognostic effect in this group of patients." (PMID 36180554, 2022). "In addition, we found that serum CPT1A levels were positively correlated with metastasis, advanced TNM stage and histological grade, and may enable discrimination between different breast cancer molecular subtypes." (PMID 33858374, 2021). "We found that CPT1A is overexpressed in breast cancer tissues compared with normal breast tissues." (PMID 33858374, 2021). "To better understand the potential use of serum CPT1A as a clinical biomarker, we further compared the predictive value and likelihood ratios of CPT1A with three conventional tumor markers, CA15–3, CEA, and CA125, in discrimination of breast cancer patients from healthy controls." (PMID 33858374, 2021). "However, the expression patterns of intracellular and secreted CPT1A are not consistent among a panel of breast cancer cell lines." (PMID 33858374, 2021). "Furthermore, PRL partially rescued the knock-down of CPT1 enzyme activity induced by siRNA-mediated targeting of CPT1A in breast cancer cells, but not in normal breast epithelial cells." (PMID 21294903, 2011). "Also, FDXR and CPT1A did not correlated in the ER+ breast cancer patients, the reason could be that both CPT1A and mitochondrial OXPHOS genes were downstream genes regulated by FDXR, and also other factors may co-regulate CPT1A expression." (PMID 37207154, 2023).
breast cancer (continued). "Interestingly, the clustering of CPT-1A with JAK-STAT signalling, MAPK signalling, matrix remodelling and metastasis and Wnt signalling identifies a poor prognostic subgroup of mucinous carcinomas, a type of breast carcinoma which normally has a very good prognosis." (PMID 36180554, 2022).
Hepatic steatosis (68 papers, 2013 to 2026). Steatosis is a term used to denote lipid accumulation within hepatocytes. "CPT1A expression is closely associated with inflammatory status, as patients with CPT1A deficiency often exhibit hepatic steatosis and enhanced systemic inflammation." (PMID 41378259, 2025). "In the same line, previous data from our group described the utility of the analysis of impaired CPT1A response to fasting as a marker of metabolic risk (liver steatosis and insulin resistance) in metabolically obese but normal-weight rodents." (PMID 32751185, 2020). "Moreover, hesperidin prevented hepatic steatosis in western diet-fed rats by preventing the upregulation of lipogenesis-related genes Srebf1, and Scd1 caused by Western diet and the downregulation of Pparα and Cpt1a expression and CPT1a protein levels." (PMID 32785059, 2020). "Thus, the increased expression of Acacb in HF-fed Nrf2−/− livers, coupled with the exaggerated loss of Cpt1a and Acaa1 expression, may contribute to the increased hepatic steatosis in these animals." (PMID 24958099, 2014). "In MAFLD, PPARα suppresses hepatic steatosis by upregulating genes involved in β-oxidation (CPT1A, carnitine palmitoyltransferase 1A; ACOX1, acyl-CoA oxidase 1) and inhibiting de novo lipogenesis (DNL)." (PMID 40564141, 2025). "It has been reported that PPARα activation upregulates its target genes (LPL, ACOX1, and CPT-1a) expression, enhancing lipid degradation and fatty acid oxidation, which ameliorates hepatic steatosis, dyslipidemia, and insulin resistance." (PMID 39942052, 2025). "In a recent publication, hepatic stellate cell-specific Cpt1a knockout mice showed dramatic hepatic steatosis increases when fed with both control and high-fat diets, indicating how beta-oxidation is key to the overall lipid metabolism of the liver." (PMID 37569418, 2023). "Interestingly, acute ethanol binge completely blocked the Western diet-associated upregulation of Ppar-α and Cpt1a mRNAs, which, together with high concentrations of circulating fatty acids, may underlie the exacerbation of hepatic steatosis in our Western diet plus ethanol binge animals." (PMID 37314747, 2023). "Although some reports suggest that TH increases the activity of hepatic lipases, lipophagy, and β-oxidation of fatty acids, which help fatty liver to reduce steatosis, little changes were found here in genes involved in fat oxidation (CPT1a, CD36, and AOX)." (PMID 37649581, 2023). "In the early stages of fatty liver, in which the liver is otherwise healthy, the liver compensates by decreasing CPT1A activity." (PMID 37107193, 2023). "CPT1a-overexpressing mice were protected against obesity-induced weight gain, obesity-induced insulin resistance, and hepatic steatosis." (PMID 36359900, 2022). "Previous published studies have demonstrated an increased lipogenesis and a decreased fatty acid β-oxidation in hepatic steatosis and these processes are tightly controlled by a number of genes including CPT-1a and PARs such as PPARα." (PMID 33224240, 2020). "Note, a recent study demonstrated recovery of CPT1A to ameliorated hepatic steatosis in mice after treatment with the hepatic stimulator substance (HSS)." (PMID 30547786, 2018). "It is worth noting that a recent study has shown that p38 inhibition enhanced parenteral nutrition-induced hepatic steatosis and attenuated the expression of Cpt1a, Acox1, and Ppargc1a in a rat model." (PMID 30563203, 2018). "Key genes such as CPT1A and PPARα may be potential targets, given their reported modulation by polyphenols in similar hepatic steatosis models." (PMID 41575476, 2026). "While our study did not assess genetic variants, emerging data suggest DNA methylation changes (e.g., CPT1A hypomethylation) may concurrently drive hepatic steatosis and vascular calcification." (PMID 40406231, 2025).
Hepatic steatosis (continued). "CGA also increases the expression levels of genes involved in fatty acid metabolism, including Cpt1a, Cpt1b, and Fgf21, while decreasing the expression levels of Pparγ1, Pparγ2, and their target genes Cd36, Fabp4, and Mgat1, thereby ameliorating hepatic steatosis and insulin resistance." (PMID 39459158, 2024). "In summary, fructose supplementation on BCD compared to the LFD enabled greater induction in KHK-C and DNL enzymes while lowering the CPT1A protein levels, which may explain the development of hepatic steatosis in these mice." (PMID 39796558, 2024). "AMPK activation also enhances PPARα expression by triggering the AMPK/PGC1α signaling axis, promoting fatty acid oxidation, and ameliorating hepatic steatosis to upregulate the expression of carnitine palmitoyltransferase 1A (CPT1A) and acyl coenzyme a oxidase 1 (ACO1)." (PMID 39139977, 2024). "Researchers have investigated the epigenetic mechanisms associated with the CPT-1A promoter and found that butyrate, a dietary HDAC inhibitor, can protect against the ethanol-driven epigenetic deregulation of CPT-1A expression and reduce hepatic steatosis." (PMID 37175712, 2023). "A retrospective study demonstrated that moderate to high-intensity exercise improved hepatic steatosis by downregulating the lipid synthesis-related gene Srebp1c and increasing the fatty acid β-oxidation gene CPT1a in peripheral blood mononuclear cells (PBMCs)." (PMID 36605939, 2022). "Tributyrin inhibited HDAC1, enhanced the CPT1a expression, and improved hepatic steatosis in mice." (PMID 36077368, 2022). "PPAR-γ is known as an “energy balance receptor” and is a crucial regulator of many PPRE-containing genes such as FABP4 and CPT1A having an essential function in fat metabolism and lipogenesis, resulting in the decline of the circulating blood lipids and inhibition of the liver steatosis." (PMID 34306045, 2021). "CPT1A protects obese mice against hepatic steatosis and insulin resistance." (PMID 32455134, 2020). "In a recent study, hepatic CPT1A was directly activated by baicalin to promote the lipid going into mitochondria for fatty acid degradation, which could ameliorate hepatic steatosis and obesity." (PMID 31443273, 2019). "Moreover, the reduction in liver steatosis induced by resveratrol in rats fed an obesegenic diet is mediated, at least in part, by the increase in CPT1a protein expression and activity, via a decrease in miRNA-107-3p expression." (PMID 28375178, 2017). "Furthermore, the reduction in liver steatosis induced by resveratrol under our experimental conditions is mediated, at least in part, by increased CPT1a protein expression and activity, via a decrease in miRNA-107-3p expression." (PMID 28375178, 2017). "While down-regulation of DGAT1 in spheroids following LGALS3 silencing could have protective effects in condition of hepatic steatosis, changes in CPT1A and PPARA mRNA levels, might be a consequence of the lipid content reduction or represent an independent effect exerted by Gal-3." (PMID 40608687, 2025). "Furthermore, studies have indicated that in hepatic steatosis, Ginsenoside Rb1 could activate mitochondrial β-oxidation functions and ameliorate fatty liver by regulating some key enzyme expression and CPT1A active." (PMID 39071885, 2024). "However, the overexpression of CPT1A in the liver, induced by saturated fatty acids and reactive oxygen species, triggers mitochondrial activity and may lead to hepatic steatosis and fibrosis." (PMID 38256272, 2024). "On the other hand, genes associated with the metabolism of lipids/fatty acids including Acadl, Cpt1a and Hadha were downregulated in the inulin diet group, a modulation that goes in line with the described effects of inulin consumption on lowering the circulating lipid profile and hepatic steatosis." (PMID 37101209, 2023).